LOX (lysyl oxidase)
Diseases named in the same sentence as LOX in open-access papers (continued):
Sharing a sentence is not in itself a finding about the gene and the disease.
cancer (continued). "Lysyl oxidase (LOX) may be a cell-secreted amine oxidase which differentially regulated by status of disease or cancers and plays a pivotal role in cancer progression, including metastasis, and is therefore is an attractive therapeutic target." (PMID 35189882, 2022). "The involvement of one or more LOX members was verified in different cancers." (PMID 35433829, 2022). "Of note, periostin promotes chemoresistance through several mechanisms, including: 1-induction of EMT; 2-increased cancer cell stemness; 3-upregulation of LOX and increasing stiffness; 4-activation of Akt and Erk, the PI3K/Akt/survivin, and the PI3K/Akt/survivin pathways." (PMID 36224629, 2022). "Several studies highlighted the importance of this lysyl oxidase in cancer." (PMID 36114508, 2022). "Research identified high expression of LOX in several malignant tumors." (PMID 34930321, 2021). "The result indicates that LOX may function as a potential oncogene and may be proposed as a promising potential molecular target for therapy in various types of cancers." (PMID 35047494, 2021). "Lysyl oxidase (LOX), an enzyme which cross-links newly synthesized collagen molecules, is upregulated in response to elevated collagen deposition, and its overexpression has been shown to correlate with metastasis and decreased survival in cancer patients." (PMID 34638240, 2021). "MSCs have also been shown to cause aberrant expression of micro-RNAs by BCCs, providing BCCs with enhanced cancer stem cell properties, and to promote the production of lysyl oxidase by BCCs, which was found to enhance the metastasis of weakly metastatic cancer cells to the lungs and bones." (PMID 33513753, 2021). "Cox found that lysyl oxidase (LOX) in the hypoxic cancer secretome could disrupt normal bone homeostasis and lead to the formation of focal pre-metastatic lesions in patients with estrogen-receptor-negative breast cancer." (PMID 34490098, 2021). "Also, immunofluorescence staining and transwell assays with drug-modified collagen showed that LOX-mediated high collagen stiffness led to deformation and promoted cancer cell invasion." (PMID 34930321, 2021). "Besides fibrotic diseases, altered LOX activity is related to inflammatory diseases, as well as cancer progression." (PMID 34064989, 2021). "Targeting transglutaminase or lysyl oxidase with therapeutics could be options to fight cancer by reversing the biomechanical stiffening of the TME." (PMID 35008569, 2021). "The risk of macrophages high density, high microvessel density (MVD), low neomicrovessel maturation, MMP-9 expression and low type IV collagen was elevated after LOX overexpression, suggesting that LOX activated cancer stromal cells and facilitated the progression of GC." (PMID 35126449, 2021). "We found that high LOX expression significantly reduces survival for luminal cancer patients." (PMID 34617419, 2021). "LOX/LOXL proteins have been implicated in the pathogenesis of various diseases, including cancer." (PMID 33669630, 2021). "LOX upregulation in cancer has been shown to be involved in cancer progression and metastasis." (PMID 34869590, 2021). "It has been previously speculated that LOX might be a potential therapeutic target in fibrotic diseases and cancer; however, specific treatment options are missing." (PMID 34064989, 2021). "In addition, we added HIF1A and LOX as additional targets due to their relevance in cancer aggressiveness and adaption of ECM to promote invasion." (PMID 31959767, 2020). "The ECM re-modeler, LOX is a well-known modulator of cancer metastasis." (PMID 32415208, 2020). "Lysyl oxidase (LOX) family proteins that mediate the cross-linking of collagen and elastin, two basic components of the ECM, are considered key regulators in remodeling of the cancer-associated ECM and premetastatic niche formation." (PMID 32754259, 2020). "LOX-dependent collagen crosslinking enhances proliferation of cancer cells and metastatic capacity." (PMID 32286443, 2020).
cancer (continued). "LOX has been shown to mediate hypoxia-induced cancer metastasis." (PMID 33371259, 2020). "Targeting LOX in canine cancer is an exciting prospect for the development of drugs that could prevent cancer metastasis and progression." (PMID 32542505, 2020). "The LOX status plays a critical role in several types of cancer." (PMID 32184727, 2020). "The reason is unclear, but it could be a way to maximize LOX maturation close to its excretion site, where it plays a major role in cancer cell migration and metastasis." (PMID 33271772, 2020). "High abnormal expression of LOX and LOXL2 was also observed in the epithelium of dysplastic tissue, suggesting a possible role in dysplasia that may ultimately be a factor in cancer development in combination with mutations and environmental influences." (PMID 31086173, 2019). "LOX enzymes represent exciting targets for the treatment of cancer and fibrosis." (PMID 31130685, 2019). "Furthermore, co-injection of high LOX expressing fibroblasts together with cancer cells in vivo resulted in stiff invasive tumors and FAK activation, compared to co-injection with low LOX expressing fibroblasts." (PMID 31130685, 2019). "Correlations between MMP/LOX expression and the 5-year survival rates of cancer patients∗∗." (PMID 31106200, 2019). "LOXL2, a member of the lysyl oxidase (LOX) family that encodes genes for copper-dependent amine oxidases, which participate in ECM stabilization by covalent cross-linking of collagen is strongly associated with cancer progression." (PMID 29503225, 2018). "However, recent studies demonstrated that LOX also plays critical roles in hypoxia-induced cancer metastasis." (PMID 30423905, 2018). "The propeptide domain of LOX (LOX-PP) has been shown to inhibit tumorigenesis in various cancers." (PMID 29993014, 2018). "It has also been reported that LOX plays critical roles in cancer cell colonization in bone." (PMID 30423905, 2018). "LOX upregulation in cancer cells is of importance in tumorigenesis and may promote progression of the primary tumor." (PMID 30545079, 2018). "In addition, LOX supports the attachment and survival of cancer cells to and in the bone matrix and dissemination in the bone marrow." (PMID 30181809, 2018). "Lysyl oxidase (LOX) family genes, particularly lysyl oxidase-like protein 2 (LOXL2), have been implicated in carcinogenesis, metastasis, and the epithelial-to-mesenchymal transition (EMT) in various cancers." (PMID 29959362, 2018). "The results demonstrated in this paper indicates the LOX and collagens as important factors that might contribute to cancer resistance mechanism." (PMID 30583585, 2018). "Due to its influence on such diverse functions, LOX also can play multiple roles in cancer." (PMID 30128085, 2018). "It was originally shown that the LOX-PP could inhibit NF-κB activity and induced phenotypic reversion of cancer cells." (PMID 28947950, 2017). "Finally, it has been reported that expression of a recombinant propeptide displaying LOX activity interferes with the DSB repair response in cancer cells by abrogating ATM phosphorylation." (PMID 28701698, 2017). "CCT365623 and its analogues are undergoing clinical development for use in LOX driven cancers." (PMID 28416796, 2017). "Similarly, in human head and neck squamous cell carcinomas, higher levels of LOX correlate with later stage cancers, increased metastasis to the lymph node, and decreased overall patient survival." (PMID 28110559, 2017). "The results suggest that the hydrazide group may be a useful core functionality that can be developed into potent and selective inhibitors of lysyl oxidase and eventually find application in cancer metastasis research." (PMID 28110559, 2017). "Blocking LOX's enzymatic function can reduce migration of cancer cells." (PMID 28110559, 2017).
cancer (continued). "However, the hypoxia-driven HIF-1α upregulation also activates downstream pathways involved in metabolism (e.g. CAIX), angiogenesis (e.g. VEGF/VEGFR2 pathway) and extracellular matrix activity (e.g. LOX), which can modulate cancer behavior." (PMID 28143503, 2017). "Lysyl oxidase has emerged as an important enzyme in cancer metastasis." (PMID 28110559, 2017). "In addition to extracellular modifications, LOX also appears to regulate cancer progression within cells such as via modulation of actin polymerization that promotes migratory phenotypes." (PMID 28425924, 2017). "Since nuclear LOX presence may be involved in affecting specific gene expression patterns, we speculate that there may exist a positive LOX-NF-κB feedback loop promoting cancer metastasis in CRC." (PMID 28947950, 2017). "Our data show that LOX depletion sensitizes cancer cells to anti-microtubule agents." (PMID 27296552, 2016). "Our findings suggest that LOX has a role in cancer cell mitosis and may be targeted to enhance the activity of microtubule inhibitors for cancer therapy." (PMID 27296552, 2016). "LOX regulates cancer progression in a variety of human malignancies." (PMID 27296552, 2016). "Knockdown of LOX reduced the viability of the 3 cancer cell lines with a greater effect with siLOX." (PMID 27296552, 2016). "Further investigations are needed to understand the circumstances under which LOX inhibition may be used as a therapeutic target for cancer patients." (PMID 26804196, 2016). "In this short review, we discuss recent research on the correlations between LOX and cancer." (PMID 28036074, 2016). "Given that we previously observed uniformly high expression ofLOX in undifferentiated and poorly differentiated thyroid cancer, which are characterized by high mitotic count, we hypothesized that LOX may have a role in cancer cell mitosis." (PMID 27296552, 2016). "The mature active LOX and LOX-PP play opposite roles in cancer progression." (PMID 28036074, 2016). "Similarly, LOX proteins expressed by cancer cells accumulate at potential metastatic sites, where they mediate collagen IV crosslinking, which in turn, triggers the recruitment of hematopoietic cells to form the pre-metastatic niche." (PMID 26956475, 2016). "Taken together, these results indicate that LOX proteins have multiple pro-tumorigenic effects and suggest that their inhibition could be a potential strategy to impair cancer progression and improve patient outcome." (PMID 26956475, 2016). "Therefore, the development of new compounds having both antiinflammatory and antioxidant activities and being LOX inhibitors is an interesting approach for cancer prevention, treatment of chronic inflammation and other related pathological conditions." (PMID 27047380, 2016). "Therefore, using LOX as a target for anti-cancer drug discovery has great potential for cancer therapy in the future." (PMID 28036074, 2016). "In summary, LOX, and more specifically LOX-PP, has been showed to have anti-tumorigenic properties, which could be exploited to treat cancer cells." (PMID 26258070, 2015). "Importantly, the LOX–hypoxia axis defines the poor prognosis of surgically resectable cancers and can explain many of the features that contribute to making PDAC inherently refractory to conventional cytotoxic chemotherapy." (PMID 26077591, 2015). "The family of lysyl oxidase (LOX) enzymes is a central player in remodeling of cancer-related ECM." (PMID 26265048, 2015). "Additionally, LOX has been reported to have direct effects on cancer cells themselves through regulation of senescence." (PMID 26077591, 2015). "Furthermore, it has been demonstrated that the propeptide of LOX (ppLOX), which is the liberated form of the LOX precursor by cleavage with protease bone morphogenetic protein 1 (BMP1), inhibits cancer-associated DNA repair." (PMID 25978957, 2015).
cancer (continued). "Among the genes that were down-regulated in the absence of Vav1 was CSF1, as well as several genes whose products might participate in signaling events, including lysyl oxidase (LOX), known to participate in cancer development." (PMID 25313137, 2014). "The chronic inflammation and the fibrotic changes, including perhaps LOX activity, could explain the considerable aggression of many cancer cells, once transformed." (PMID 24885752, 2014). "On the other hand, reduced LOX expression has also been reported in many carcinomas." (PMID 25141126, 2014). "However, a number of studies have identified differential expression of LOX in human cancers and their stromal reaction." (PMID 21139993, 2010). "Additionally, LOX activity triggers downstream signaling pathways like TGF-β and MAPK, which are strongly linked to epithelial-mesenchymal transition (EMT) and the preservation of cancer stem cells." (PMID 40661776, 2025). "Therefore, targeting MMPs and LOX has been conducted in clinical trials for cancer therapy." (PMID 38246995, 2024). "However, mature active LOX and LOX-PP play opposing roles in cancer progression." (PMID 35189882, 2022). "Similar to the cytokine profiling results, most of the cancer‐associated proteins, such as ANGPTL4, KLK5, GAL3, VIM, HERs, CAPG, HO, CTSD, and AFP were produced at higher levels on the aged matrix, but were reduced to young matrix levels after LOX siRNA treatment." (PMID 34617419, 2021). "Moreover, a quick and accurate determination of LOX levels in the tissue specimen may facilitate the early diagnosis of cancer." (PMID 34572752, 2021). "Therefore, the use of LOX as a biomarker is likely to be cancer type specific." (PMID 33513979, 2021). "However, 128 protein partners of LOX and LOXLs were not functionally linked to any member of the network or any drug, and were not displayed, although 11 of them were associated with cancer." (PMID 33383846, 2020). "Other described transcription factors regulating LOX at the promoter level includes GATA-binding protein 3 (GATA-3)—which is also associated with T-helper 2 polarization—and the pro-survival transcription factor forkhead box M1b (FoxM1b), often over-expressed in cancer." (PMID 31650200, 2020). "Neither LOX, nor LOXLs, were directly associated with an anti-cancer drug." (PMID 33383846, 2020). "In addition, HIF-1 produces lysyl oxidase (LOX) and LOX-like proteins from cancer cells." (PMID 32069878, 2020). "The major goal of our study, which combines both in vitro and in silico computational approaches, was thus to build and analyze the interaction network of LOX and LOXLs to generate new insights and hypothesis on the LOX family functions, and its role in cancer." (PMID 33383846, 2020). "Finally, we discuss how the development of selective LOX inhibitors may lead to novel and effective therapies in cancer treatment." (PMID 31130685, 2019). "Selective LOX inhibitors may lead to novel and effective therapies for cancer treatment." (PMID 31130685, 2019). "Thus, simultaneous administration of recombinant LOX-pp and LOX inhibitors may be a promising anti-cancer treatment option." (PMID 29732010, 2018). "However, the precise role of LOX in cancer remains controversial." (PMID 28947950, 2017). "Thus, we expect that a strategy of reducing LOX expression in cancer cells could make existing cancer drugs that target the microtubules even more effective, with less toxicity as lower concentrations of the agent could be used." (PMID 27296552, 2016). "Thus, resistance to radiation and certain drugs, EMT transition, and harboring cancer stem cell like characteristics may contribute to the LOX-related poor prognosis." (PMID 27147578, 2016). "LOX induction by Hpa2 may turn very important in pathological conditions other than cancer." (PMID 26968815, 2016).
cancer (continued). "The LOXL4 protein is an important member of the lysyl oxidase (an extracellular copper-dependent amine oxidase) family that catalyzes the first step of the crosslinks between collagens and elastin during the biogenesis of connective tissue and is frequently deregulated in cancer." (PMID 25311867, 2014). "In this study, downregulation of LOX expression was accompanied by a parallel downregulation of its substrates tropoelastin and type I collagen, whereas collagens are frequently overexpressed in carcinomas, which may explain these divergent results." (PMID 25141126, 2014). "Therefore, in addition to making invasive/metastatic cancer cells more invasive, hypoxia may induce LOX expression in poorly invasive cancer cells, thereby enabling them to acquire invasive competence." (PMID 23545606, 2013). "While LOX inhibitors show promising potential in fibrotic disease trials (NCT04676529, NCT04054245) 184, their application in malignant tumor treatment remains in the exploratory stage, necessitating urgent advancement of related clinical investigations." (PMID 41362727, 2026). "Copper-dependent enzymes, such as cytochrome c oxidase, superoxide dismutase, and lysyl oxidase (LOX), are key cancer modulators." (PMID 41480765, 2026). "To examine variations in LOX expression between tumors and normal tissues across various cancer types, we employed GSCA to analyze LOX mRNA levels." (PMID 40270974, 2025). "LOX is acknowledged as a pro-metastatic factor in CRC, prostate cancer, and liver cancer, promoting cancer cell invasion and dissemination." (PMID 40370501, 2025). "Our study unveiled an increased expression of LOX and LOXL1‐3 across various cancer types, whereas LOXL4 expression demonstrated an inverse trend." (PMID 40179101, 2025). "Emerging evidence suggests that LOX activity is regulated by various signaling pathways, including TGF - β and Wnt/β - catenin, which are frequently dysregulated in cancer." (PMID 40661776, 2025). "Enhanced collagen crosslinking, frequently facilitated by enzymes such as lysyl oxidase (LOX), rigidifies the extracellular matrix (ECM) and fosters cancer cell migration, epithelial–mesenchymal transition (EMT), and metastatic proliferation." (PMID 41465319, 2025). "Our thorough investigation brought to light the possible therapeutic importance of LOX family‐specifically, LOX and LOXL2 in the advancement of cancer therapy strategies." (PMID 40179101, 2025). "Cu constitutes a fundamental element in numerous enzymes and proteins that are intricately involved in cancer biology, such as SOD1, lysyl oxidase (LOX), and CCS." (PMID 40370501, 2025). "A recent study highlights the potential benefits that bi-thiazole (LXG6403), a LOX inhibitor, offers in chemotherapy and ECM restructuring in cancer." (PMID 40227764, 2025). "Targeted inhibition of LOX and LOXL by copper can successfully inhibit the invasion and spread of cancer cells." (PMID 38662225, 2024). "The physiological and chemical remodeling of the ECM during cancer progression involves proteases breaking down the ECM and increased collagen fibril cross-linking mediated by lysyl oxidase (LOX)." (PMID 38455762, 2024). "In fact, some biological responses attributed to LOX rely on this key molecule for redox signaling and oxidative stress such as the LOX-dependent regulation of VSMC chemotaxis, vascular stiffness, and cancer cell migration." (PMID 38790628, 2024). "Antioxidant, anti-inflammatory (LOX, COX-2 inhibition), antihypertensive (ACE inhibition), and antiproliferative effects on AGS and HT-29 cancer cells were evaluated." (PMID 39683849, 2024). "In contrast, the fibroblasts expressed relatively higher levels of LOX and LOXL2, suggesting that the fibroblasts exhibit a different hypoxia expression profile than the cancer cells." (PMID 39011470, 2024).